ADRB1 (adrenoceptor beta 1)
Diseases named in the same sentence as ADRB1 in open-access papers (continued):
Sharing a sentence is not in itself a finding about the gene and the disease.
cervical cancer (1 paper, 2022). A primary or metastatic malignant neoplasm involving the cervix. "ADRB1 was found to be related to radiomic features and was considered as a risk factor associated with the risk of cerebral neurovascular metastasis in cervical cancer." (PMID 35903112, 2022). "Therefore, ADRB1 expression in cervical cancer was correlated with imaging features and was associated as a risk factor for cerebral neurovascular metastases." (PMID 35903112, 2022). "Hence, ADRB1 expression is associated with radiomics features and is considered a risk factor for cerebral neurovascular metastasis of cervical cancer." (PMID 35903112, 2022). "Therefore, features of radiomics that are related to ADRB1 may be associated with the risk of cerebral neurovascular metastases in cervical cancer." (PMID 35903112, 2022). "As a risk factor associated with the development of cerebral neurovascular metastases of cervical cancer, ADRB1 expression was significantly higher in brain metastases from cervical cancer." (PMID 35903112, 2022). "In light of this, the radiomics feature original_glszm_GrayLevelVariance in the model is likely to be able to predict ADRB1 expression and, thereby, brain metastasis in cervical cancer." (PMID 35903112, 2022). "ADRB1 gene expression was significantly higher in cervical cancer brain metastasis than in other metastasis sites." (PMID 35903112, 2022). "According to the TCGA data, mRNA differential gene expression analysis of patients with cervical cancer revealed an increase in the expression of neurovascular-related gene Adrenoceptor Beta 1 (ADRB1) in the brain metastasis group." (PMID 35903112, 2022). "In order to further identify the role of ADRB1 in cervical cancer brain metastasis, the GSEA analysis of RNA transcription data from patients with cervical cancer revealed that the T cell receptor complex pathway was upregulated, while the iron-sulfur cluster assembly pathway was downregulated." (PMID 35903112, 2022). "Similarly, this study identified ADRB1 as a potential oncogene involved in the neurovascular metastasis of cervical cancer." (PMID 35903112, 2022). "Thus, ADRB1 serves as an immunomodulator in the process of cerebral neurovascular metastasis in cervical cancer." (PMID 35903112, 2022).
Cirrhosis (1 paper, 2020). A chronic disorder of the liver in which liver tissue becomes scarred and is partially replaced by regenerative nodules and fibrotic tissue resulting in loss of liver function. "In conclusion, this study suggests that the over-expression of splenic ADRB1 and ADRB2 is significantly involved in the pathogenesis and mechanism of cirrhosis-associated immunological dysfunction." (PMID 32138352, 2020). "Among the tissues (liver, intestine, MLN, spleen) involved in the immune dysfunction in cirrhosis, simultaneous over-expression of ADRB1 and ADRB2 protein levels was only noted in the spleens of cirrhotic mice." (PMID 32138352, 2020). "Particularly, the elevation of splenic LBP as well as up-regulation of splenic ADRB1 and ADRB2 expression indicated the involvement of the spleen in the pathogenesis of cirrhosis-associated immune dysfunction." (PMID 32138352, 2020). "In conclusion, suppression of ADRB1 and ADRB2 expressions in spleen and splenic T lymphocytes by acute and chronic propranolol treatment ameliorate systemic and splenic immune dysfunction in cirrhosis." (PMID 32138352, 2020).
dry eyes (1 paper, 2022). "In PCS/ME/CFS patients, the secretomotor symptoms (dry eyes, dry mouth) correlated negatively with levels of AABs against AGTR1, EDNRA, ADRA1A, ADRB1/2, and CHRM3 (black bars)." (PMID 36238301, 2022). "Similarly, the negative correlation of the secretomotor symptoms (dry eyes, dry mouth) with levels of AAB against vasoregulatory receptors AGTR1, EDNRA, ADRA1A, ADRB1/2, and CHRM3 indicate a vascular mechanism." (PMID 36238301, 2022).
frontotemporal dementia (1 paper, 2023). Frontotemporal dementia (FTD) comprises a group of neurodegenerative disorders, characterized by progressive changes in behavior, executive dysfunction and language impairment, as a result of degeneration of the medial prefrontal and frontoinsular cortices. "To determine the effect of the Adrb1-A187V mutation on the accumulation of tau pathology, we crossed heterozygous Adrb1-A187V mice (Adrb1+/m) with PS19 tau mice expressing 1N4R human tau with a P301S mutation that causes a form of frontotemporal dementia (Adrb1+/m;PS19)." (PMID 37014857, 2023).
infantile hemangioma (1 paper, 2020). "Previous works on infantile hemangioma (IH) and CNS-HB primary tumors demonstrated the in vitro antitumoral effects of propranolol, an ADRB-1,2 blocker." (PMID 32854260, 2020).
Insulin resistance (1 paper, 2020). Increased resistance towards insulin, that is, diminished effectiveness of insulin in reducing blood glucose levels. "ADRB1 also contributes to increased secretion of renin and ghrelin hormones, which are associated with T2D and insulin resistance." (PMID 33113859, 2020).
liver cancer (1 paper, 2014). An epithelial or non-epithelial malignant neoplasm that arises from the liver. "In liver cancer, various kinds of GPCR, including ADRB1 and DRD1PLC and their downstream element PLC, were abnormally methylated." (PMID 24842468, 2014).
multiple myeloma (1 paper, 2023). "ADRB1 was expressed at a low level at all stages of disease progression, with a non‐significant increase in multiple myeloma patients." (PMID 36245401, 2023). "To investigate the expression levels of ADRB1, ADRB2, and ADRB3 in human multiple myeloma cell lines, we consulted the Lombardi and Heidelberg‐Montpellier cohorts." (PMID 36245401, 2023).
neuroblastoma (1 paper, 2019). Neuroblastoma (NB) is the most common solid, extracranial childhood tumor. "Of note, ADRB1 is expressed at low levels in the angiosarcoma cell line (not shown) but is expressed at higher levels in the SHEP neuroblastoma cell line, where its expression can be reduced by siRNA." (PMID 31358114, 2019). "Similar results were obtained when using a non-endothelial cell type (SHEP neuroblastoma cell line) whereby knock-down of ADRB1 and ADRB2 alone or in combination did not affect the ability of propranolol to block the proliferative response and its ability to enhance response to chemo-therapies." (PMID 31358114, 2019).
pemphigus (1 paper, 2021). Pemphigus is a group of rare autoimmune diseases that cause blistering of the skin and mucous membranes (mouth, nose, throat, eyes, and genitals).This conditioncan occur at any age, but often strikes people in middle or older age. "Analysis of neuroendocrine genes revealed that ADRB1, MCR5, and CYP1B1 were significantly downregulated in pemphigus vs. healthy controls." (PMID 34660634, 2021).
peripheral vascular disease (1 paper, 2024). Any disorder affecting blood flow through the veins or arteries outside of the heart. "Genotype-phenotype association analysis in S3 Table, shows that ADRB1 rs1801253 exhibited noteworthy association with peripheral vascular disease (P = 0.001), angiotensin converting enzyme inhibitors (ACEi) (P = 0.005) and other medication (P = 0.027)." (PMID 38935682, 2024).
psoriasis (1 paper, 2024). An autoimmune condition characterized by red, well-delineated plaques with silvery scales that are usually on the extensor surfaces and scalp. "The results suggest that CAMK2G and ADRB1 are targets for the clinical treatment of psoriasis, especially that affected by neuropsychiatric factors." (PMID 38544478, 2024).
small cell lung carcinoma (1 paper, 2022). Small cell lung cancer (SCLC) is a highly aggressive malignant neoplasm, accounting for 10-15% of lung cancer cases, characterized byrapid growth, and early metastasis. "Colocalization analysis suggested that ADRB1 and small cell lung carcinoma were unlikely to share a causal variant within the ADRB1 locus (1.5% posterior probability of a shared causal variant)." (PMID 35113855, 2022).
tauopathy (1 paper, 2023). Neurodegenerative disorders involving deposition of abnormal tau protein isoforms (tau proteins) in neurons and glial cells in the brain. "Our findings suggest that the Adrb1-A187V mutation protects against tauopathy by both mitigating tau accumulation and attenuating tau spreading." (PMID 37014857, 2023). "To further confirm this finding and gain more insight into the role of FNSS mutations in tauopathy, we crossed another FNSS mouse model, Adrb1-A187V mice, with PS19 mice to investigate the effects of this mutation on tau pathology." (PMID 37014857, 2023).
tumor (36 papers, 2013 to 2026). "CNV analysis highlighted malignant cells in the tumor microenvironment, and intercellular interaction analysis explored ADRB1+ T cells’ role in immune support." (PMID 40406147, 2025). "They reported that deletion of ADRB1 in T cells, or pharmacological blockade of ADRB1 using β-blockers (BBs), enhanced the secretion of effector molecules and cytokines and improved T cell function in chronic infection and tumor settings." (PMID 41194930, 2025). "For example, the study demonstrated that the use of ADRB1 inhibitors, such as atenolol, can reverse T-cell exhaustion and enhance the anti-tumor effects of PD-1 inhibitors." (PMID 40406147, 2025). "Analysis of gene expression in our single-cell BCC data revealed several targetable Gαs-coupled GPCRs present in tumor cells, including prostaglandin E receptor 4 (Ptger4), adenosine receptor 2b (Adora2b) and β-Adrenergic Receptors (Adrb1–2), among others." (PMID 40060632, 2025). "Using Western blot to detect ADRB1 expression in tumor tissues of patients after neoadjuvant therapy, the results showed that ADRB1 expression in tumor tissues significantly increased following the therapy." (PMID 40406147, 2025). "Our study highlights the critical role of ADRB1 in the ESCC tumor microenvironment, particularly in regulating T-cell exhaustion, tumor-immune cell interactions, and immune therapy resistance." (PMID 40406147, 2025). "The study demonstrated that the sympathetic nervous system induces functional exhaustion in CD8+ T cells via the ADRB1 signaling pathway, thus diminishing the anti-tumor immune response." (PMID 40406147, 2025). "Further bioinformatic analysis revealed that the expression of neurovascular-related gene ADRB1 was elevated in the tumor brain metastasis group." (PMID 35903112, 2022). "Various database applications (Gene Set Enrichment Analysis, Tumor IMmune Estimation Resource, Connectivity Map, KnockTF) supported the selection of treatment strategies targeting ADRB1." (PMID 33234738, 2020). "(2020) suggested that chemotherapy and immunotherapy might induce upregulation of ADRB1 on T cells, enhancing their ability to adapt to the tumor microenvironment." (PMID 40406147, 2025). "Notably, the median expression of the targets of BBs (ADRB1 and ADRB2 genes encoding beta adrenergic receptors), varies significantly between tumor sites." (PMID 40282534, 2025). "The role of ADRB1 in T-cell exhaustion has also been well established in various tumor types." (PMID 40406147, 2025). "This could be attributed to the persistent stimulation of T cells by tumor-associated inflammatory cytokines, such as IFN-γ and IL-6, which promote the proliferation of ADRB1+ T cells and drive them into an exhausted state." (PMID 40406147, 2025). "The correlation of ADRB1 expression and immune cell signatures implied that the anti-cancer effects of propranolol might be partly through its interaction with tumor-infiltrated immune cells." (PMID 37404751, 2023). "ADRB1 is involved in the regulation of tumor development in the lungs, breast and prostate." (PMID 35903112, 2022). "In both TCGA‐LUAD, in the GSE30219 and GSE18842 cohorts, the expression of ADRB1, ADGRD1, and ADGRE3 were reduced, whereas the expression of OR51E1 and LGR4 were elevated in tumor samples." (PMID 40364562, 2025). "Since β-blockers antagonise the β-adrenergic receptors (β-ARs) in the cardiovascular system, we first evaluated the expression pattern of β-AR genes ADRB1, ADRB2 and ADRB3 in MB tumours from a cohort of 240 patients." (PMID 35816899, 2022). "Studies have shown that β-adrenoreceptors, especially ADRB1 and ADRB2, are highly expressed in pan cancers that significantly reduce the overall survival of tumor patients." (PMID 35517499, 2022). "The protein expression profiles of the three genes, i.e., ADRB1, SAV1 and TSPAN14, involved in the PRS model demonstrated that the latter two genes are more strongly stained in tumor specimens." (PMID 34930307, 2021).
tumor (continued). "The results showed that the expression of ADRB1 and ADRB2 in HCC tumor tissue were downregulated compared to the TCGA normal tissue or adjacent-tumor tissues." (PMID 34593796, 2021). "Next, we analyzed the expression of main NE and EPI receptors, adrenergic receptors (ARs) in tumor sites, including α-adrenoceptor (α1-AR or ADRA1, α2-AR, or ADRA2) and β-adrenoceptors (β1-AR or ADRB1, β2-AR or ADRB2, β3-AR or ADRB3)." (PMID 34593796, 2021). "We showed that norepinephrine and the main adrenoceptors ADRB1 and ADRB2 are present in the tumor microenvironment." (PMID 32353988, 2020). "Therefore, the in vitro and in vivo antitumor benefits of propranolol (ADRB-1,2 antagonist) and ICI-118,551 (ADRB-2 antagonist) on VHL−/− ccRCC primary cultures and 786-O tumor cell lines have been addressed." (PMID 32854260, 2020). "The selective ADRB1 agonist showed a poor ability to promote tumour capacity that was not considerably different from that of the control group." (PMID 31624248, 2019). "Furthermore, ADRB1 genes may act synergistically with FOXA1 and ADRB2 genes to drive tumor formation and development." (PMID 35903112, 2022). "Our findings showed that the expression level of ADRB2 and TH in tumor tissues of sleep-deprived mice was significantly higher than those in the normal sleep group, while the expression levels of ADRA1, ADRA2, ADRB1, and ADRB3 showed no significant changes." (PMID 40276761, 2025).
cancer (18 papers, 2016 to 2026). A tumor composed of atypical neoplastic, often pleomorphic cells that invade other tissues. "Data from a pan‐cancer set revealed that elevated ADRB1 expression was linked to a worse survival outcome of solid tumors." (PMID 40364562, 2025). "The enhanced effect on cAMP production in the BRCA1-deficient cancer cells may be due to the overexpression of ADRB1." (PMID 35517499, 2022). "Still, our comprehensive bioinformatics analysis of cancer–nerve crosstalk-associated genes in SKCM constructed a valuable prognostic model based on eight genes (GRIN3A, CCR2, CHRNA4, CSF1, NTN1, ADRB1, CHRNB4, and CHRNG) and common clinical characteristics." (PMID 37404751, 2023). "In general, we demonstrate that cAMP promoted by ADRB1 abolishes cell cycle arrest and DNA damage induced-apoptosis in BRCA1-deficient cancer cells." (PMID 35517499, 2022). "Inhibition of ADRB1 effectively killed cancer cells by abolishing the apoptotic resistance." (PMID 35517499, 2022). "In addition, 17 small-molecule drugs targeting ADRB1 and other cancer-related genes obtained in this study also support this proposed treatment." (PMID 33234738, 2020). "Moreover, ADRB1, CCDC28B, MRAP2, SERPINA12, and WT1 were able to effectively distinguish between normal breast tissue and cancer tissue (AUC > 0.6)." (PMID 38676834, 2024).
cardiac diseases (17 papers, 2011 to 2025). "In previous literature, positive associations between the C allele of the ADRB1 Arg389Gly polymorphism have been seen in aerobic capacity performance in heart disease populations." (PMID 33572708, 2021). "Drugs blocking β1-adrenergic receptors (ADRB1) are used in the therapy of arrhythmogenic heart diseases." (PMID 38138160, 2023).
cardiovascular diseases (12 papers, 2013 to 2025). "Studies suggest that p.Arg389Gly polymorphism in the ADRB1 may be a potential genetic biomarker to assess the risk of developing cardiovascular diseases." (PMID 33113859, 2020). "The Arg389Gly polymorphism of the ADRB1 gene may be a worthy biological marker to predict the risk of developing cardiovascular diseases given a high-risk atherogenic index." (PMID 24371822, 2013). "Background/Objectives: A systematic review was conducted to compile all the evidence on the impact of ADRB1 and ADRB2 genetic variants on the response to β-blockers, used for the management of cardiovascular diseases." (PMID 40283930, 2025). "ADRB1 is also an effective target for pharmacotherapy in cardiovascular diseases, and β-blocking medications are acknowledged as first line agents for ventricular rate control in patients with AF." (PMID 31249590, 2019). "“Neurological disorder” and “cardiovascular disease” were two of the top functional pathways, both containing adrenergic, beta-1, receptor (ADRB1)." (PMID 23894375, 2013).
infection (3 papers, 2014 to 2022). The state of being infected such as from the introduction of a foreign agent such as serum, vaccine, antigenic substance or organism. "After adjustment for the potential confounders, sex, age, and time since infection, we found in addition to CHRM5-Ab significant differences with higher levels of AABs against CHRM1 and F2R/PAR-1 while lower levels of ADRB1, CHRNA1, and EDNRA in PCS/ME/CFS than in PCS/non-ME/CFS groups." (PMID 36238301, 2022).
psychiatric disorder (2 papers, 2017 to 2023). A disorder characterized by behavioral and/or psychological abnormalities, often accompanied by physical symptoms. "Unfortunately, few studies further explored the role of this increase of cortical ADRB1 in addiction or related psychiatric disorders of offspring." (PMID 37857642, 2023).
immune dysfunction (1 paper, 2020). "This study explores the modulation of β1 and β2 adrenergic receptors (ADRB1/ADRB2) by propranolol treatment on the peripheral and splenic immune dysfunction of cirrhotic mice." (PMID 32138352, 2020).
ADRB1 also shares sentences with these, for which no sentence is quoted: diabetes (9 papers); cardiac arrhythmias (8); ischemia (6); Myocardial fibrosis (6); Cognitive impairment (5); acute myocardial infarction (4); essential hypertension (4); Hypoglycemia (4); Sepsis (4); Ventricular arrhythmia (4); atherosclerosis (3); ischemic cardiomyopathy (3); asthma (2); Chagas disease (2); fibrosis (2); heart valvular disease (2); inflammation (2); ischemic stroke (2); migraine (2); Neurological disorder (2); periodontitis (2); systolic heart failure (2); agoraphobia (1); arteriosclerosis (1); atrial fibrillation/flutter (1); attention deficit-hyperactivity disorder (1); autoimmune disease (1); autoimmune myocarditis (1); Autoimmunity (1); autonomic dysfunctions (1).
A further 72 diseases each share a sentence with ADRB1 in 1 paper.